TNRC6B (trinucleotide repeat containing adaptor 6B)
Description:
Plays a role in RNA-mediated gene silencing by both micro-RNAs (miRNAs) and short interfering RNAs (siRNAs). Required for miRNA-dependent translational repression and siRNA-dependent endonucleolytic cleavage of complementary mRNAs by argonaute family proteins. As scaffolding protein associates with argonaute proteins bound to partially complementary mRNAs and simultaneously can recruit CCR4-NOT and PAN deadenylase complexes.
Synonyms: KIAA1093; GDSBA
Tractability: PROTAC: ubiquitination databases record sites on it; its protein half-life has been measured.
Gene: Protein-coding gene on chromosome 22 (40,044,817 to 40,335,808, forward strand). Ensembl gene ENSG00000100354.
Subcellular location: Cytoplasm, P-body
Pathways (Reactome):
Signal Transduction: Ca2+ pathway; Competing endogenous RNAs (ceRNAs) regulate PTEN translation; Estrogen-dependent gene expression; MAPK6/MAPK4 signaling; MTOR signalling; NR1H3 & NR1H2 regulate gene expression linked to cholesterol transport and efflux; Pre-NOTCH Transcription and Translation; Regulation of PTEN mRNA translation; TGFBR3 expression
Gene expression (Transcription): Post-transcriptional silencing by small RNAs; RUNX1 regulates genes involved in megakaryocyte differentiation and platelet function; Regulation of NPAS4 mRNA translation; Regulation of RUNX1 Expression and Activity; Transcriptional Regulation by VENTX
Cell-Cell communication: Regulation of CDH1 mRNA translation by microRNAs; Regulation of CDH11 mRNA translation by microRNAs
Cellular responses to stimuli: Oncogene Induced Senescence; Oxidative Stress Induced Senescence
Developmental Biology: Regulation of MITF-M-dependent genes involved in apoptosis
Immune System: Regulation of PD-L1(CD274) translation
Gene Ontology:
Molecular function: protein binding; RNA binding; nucleic acid binding
Biological process: miRNA-mediated gene silencing by inhibition of translation; positive regulation of nuclear-transcribed mRNA catabolic process, deadenylation-dependent decay; positive regulation of nuclear-transcribed mRNA poly(A) tail shortening; regulatory ncRNA-mediated gene silencing; miRNA processing; miRNA-mediated post-transcriptional gene silencing
Cellular component: cytosol; P-body; RISC complex
Genetic constraint (gnomAD): Loss-of-function variants: 51 observed, 193.9 expected, observed/expected ratio (o/e) 0.26, 90% interval 0.21 to 0.33. The upper end of that interval is the gene's LOEUF score, 0.33, which puts it in group 1 of 6, group 1 being the genes least tolerant of losing a copy. Missense variants: 1,887 observed, 2,270.6 expected, observed/expected ratio (o/e) 0.83, 90% interval 0.8 to 0.86. Synonymous variants: 825 observed, 845.79 expected, observed/expected ratio (o/e) 0.98, 90% interval 0.92 to 1.03.
Gene-disease validity (ClinGen):
ClinGen rates the evidence that TNRC6B causes each of these diseases.
complex neurodevelopmental disorder (autosomal dominant): Definitive. A disorder that involves more than one phenotype associated with the central nervous system, including but not limited to intellectual disability, autism, and seizures (epilepsy).
Homologues: Orthologues: chimpanzee TNRC6B (99% identical), macaque TNRC6B (99% identical), dog TNRC6B (97% identical), pig TNRC6B (97% identical), rabbit TNRC6B (97% identical), rat Tnrc6b (96% identical), guinea pig TNRC6B (94% identical), mouse Tnrc6b (93% identical), tropical clawed frog tnrc6b (72% identical), zebrafish tnrc6ba (44% identical), zebrafish tnrc6bb.1 (31% identical), zebrafish tnrc6bb.2 (22% identical). Paralogues in human: TNRC6A (37% identical), TNRC6C (36% identical), UBXN4 (6% identical), UBAC1 (5% identical), UBXN1 (4% identical).
Diseases named in the same sentence as TNRC6B in open-access papers:
TNRC6B is named in the same sentence as 50 diseases in open-access papers, as found by Europe PMC text mining. Sharing a sentence is not in itself a finding about the gene and the disease. The quoted sentences say what the papers report.
autism (7 papers, 2014 to 2025). Persistent deficits in social interaction and communication and interaction as well as a markedly restricted repertoire of activity and interest as well as repetitive patterns of behavior. "A unique genetic condition caused by TNRC6B variants includes developmental delay, intellectual disability, autism, attention deficit disorder, hyperactivity disorder, other behavioral disorders, and recurring neurocognitive and behavioral symptoms." (PMID 36979479, 2023). "TNRC6B, PTEN, AGO1, SKI, and SMAD4 were the most frequent targets, and miR-92a-3p had the most target autism risk genes." (PMID 34744804, 2021). "The TNRC6B variant was first identified by whole‐exome sequencing (WES) in a large group of patients with autism without a detailed clinical description." (PMID 38404251, 2024). "The TNRC6B variant was first identified by WES in a large group of patients with autism without a detailed clinical description." (PMID 38404251, 2024). "Open reading frames and intron/exon boundaries of the two physically disrupted genes identified, TCF20 and TNRC6B, were sequenced in 342 families (260 multiplex and 82 simplex) ascertained by the International Molecular Genetic Study of Autism Consortium (IMGSAC)." (PMID 25228304, 2014). "Only TNRC6B, NCKAP1, and one of the two ZNF292 LGD DNMs occur in autism patients with an IQ in the normal range." (PMID 30564305, 2018).
prostate carcinoma (6 papers, 2013 to 2023). A carcinoma that arises from epithelial cells of the prostate gland. "Polymorphism of the promoter region of TNRC6B was also associated with prostate cancer." (PMID 23496901, 2013). "Downregulation of TNRC6B has been suggested to contribute to tumorigenesis of different cancers, such as prostate cancer and lung adenocarcinoma." (PMID 35922826, 2022). "In a series of experiments in prostate cancer cell lines, we demonstrate that TNRC6B indeed functions as an effective ceRNA of PTEN." (PMID 28798471, 2017). "TNRC6B is expressed in many normal tissues including the prostate and is more suppressed in hormone-refractory metastatic prostate cancer than in prostate carcinoma." (PMID 23496901, 2013). "As our data processing pipeline utilized data from prostate cancer, we first investigated the ability of this predicted PTEN ceRNA TNRC6B to modulate endogenous PTEN levels in several commonly used prostate cancer cell lines which express wild-type PTEN, DU145, 22rv1 and BM1604." (PMID 28798471, 2017). "To ascertain whether the crosstalk between TNRC6B and CNOT6L was PTEN-dependent, we repeated the experiment in the prostate cancer cell line PC3, which is PTEN-null." (PMID 28798471, 2017).
developmental delay (5 papers, 2023 to 2026). "Pathogenic variants in TNRC6B have recently been associated with a neurodevelopmental disorder characterised by developmental delay, intellectual disability, and behavioural difficulties." (PMID 42074582, 2026). "SKAT-O revealed an association with H-aid for TNRC6B, a gene implicated in developmental delay which can also present with HL." (PMID 40055553, 2025). "Here, we reported two additional Chinese patients of global developmental delay with speech and behavioral abnormalities caused by two novel de novo, heterozygous variants in the TNRC6B gene, c.335C>T (p.Pro112Leu) and c.1632delC (p.Leu546fs*63), respectively." (PMID 38404251, 2024). "In conclusion, we described two unrelated Chinese patients of global developmental delay with speech and behavioral abnormalities with novel de novo TNRC6B variants in detail." (PMID 38404251, 2024). "Speech delay was documented in 94% of individuals with pathogenic TNRC6B variants, followed by other forms of developmental delay, intellectual disability, ASD, ADHD, behavioral abnormalities, musculoskeletal abnormalities, and dysmorphic features." (PMID 38300321, 2024). "Heterozygous mutations in TNRC6B cause a syndrome of global developmental delay with speech and behavioral abnormalities (OMIM 619243)." (PMID 38300321, 2024).
hepatocellular carcinoma (4 papers, 2013 to 2022). A malignant tumor that arises from hepatocytes. "Additionally, in two hepatoma cell lines, we found that over-expression of miR-18b or down-regulation of TNRC6B accelerated cell proliferation and loss of cell adhesion ability." (PMID 23496901, 2013). "Inhibition of TNRC6B has been shown to lead to acceleration of cell proliferation and deceleration of cell adhesion in hepatoma cell lines." (PMID 35922826, 2022). "As for Tnrc6b, an integrated genomic analysis for human hepatocellular carcinoma using MutSig algorithms identified several novel driver genes, including TNRC6B." (PMID 34912374, 2021). "Over-expression of miR-18b and inhibition of TNRC6B by siRNA in human hepatoma cell lines Huh7, showed the progression of cell proliferation." (PMID 23496901, 2013). "Poorly differentiated hepatocellular carcinoma (HCC) presented high miR-18b and low TNRC6B (trinucleotide repeat containing 6B) expression levels." (PMID 31181634, 2019).
breast carcinoma (3 papers, 2017 to 2021). "The significantly underexpressed genes (BMPER, FGF7, MSRB3, and TNRC6B) in breast cancer were correlated with a longer survival time based on GSE42568 and GSE37751 (P> 0.05), this correlation cannot be demonstrated." (PMID 34151730, 2021). "Furthermore, the COSMIC database v94 revealed the mutation incidence in liver, skin, and breast cancer to be 8.62, 8.61, and 4.54, respectively, suggesting a possibility that the mutations in Vps13d and/or Tnrc6b may be associated with the carcinogenesis demonstrated in the present study." (PMID 34912374, 2021). "Significantly overexpressed genes (CLDN7, MLLT10, RBM33, SH3RF1, SSBP4, and UBE2Z) were correlated with shorter survival, whereas underexpressed genes (BMPER, FGF7, MSRB3, and TNRC6B) were correlated with longer survival in breast cancer." (PMID 34151730, 2021). "Interestingly, other DEGs in breast cancer identified in this study, including MLLT10, RBM33, SH3RF1, UBE2Z, and TNRC6B, have not been proven in previous studies." (PMID 34151730, 2021).
language delay (2 papers, 2024 to 2025). "TNRC6B is a protein-coding gene involved in posttranscriptional gene silencing in association with Argonaut proteins, in which heterozygous mutations are known to cause a developmental syndrome with childhood HL, speech, and language delay." (PMID 40055553, 2025).
myelomeningocele (2 papers, 2020 to 2021). Myelomeningocele is the most severe form of spina bifida. "TNRC6B codes for an Argonaut-associated RNA and shows an association with myelomeningocele in the MA population." (PMID 32970752, 2020). "Also, it has been reported that the TNRC6B gene shows an association with myelomeningocele in the Mexican American population." (PMID 33889172, 2021). "Our study is the first to association TNRC6B and myelomeningocele." (PMID 32970752, 2020). "So, it is possible that a nonfunctional TNRC6B transcript compromises the RISC complex and indirectly decreases β-catenin role in downstream gene expression in myelomeningocele subjects." (PMID 32970752, 2020).
asthma (1 paper, 2021). "TNRC6B and MET were hypermethylated in both of our ACO patients and the asthma patients in previous EWAS, while DHX30, SFXN, C19orf28, and CLCN7 were hypomethylated." (PMID 33658578, 2021).
atherosclerosis (1 paper, 2025). A disease characterized by the build-up of fatty material and calcium deposition in the arterial wall resulting in partial or complete occlusion of the arterial lumen. "The differential DNAme also comprised key gene expression modulators, such as TNRC6B, a component of the miRISC, and ZEB2, a key transcription factor in embryogenesis, wound healing, and hematopoietic differentiation and epigenetic modulator of the transcription of atherosclerosis-associated genes." (PMID 40662355, 2025).
autism spectrum disorder (1 paper, 2020). A spectrum of developmental disorders that includes autism, and Asperger syndrome. "Recent SFARI study has identified missense mutations in miRISC proteins AGO1, TNRC6B, and CNOT3 among patients diagnosed with Autism Spectrum Disorders Patients with microdeletions of chromosomal region 1p34.3 encompassing the AGO1 and AGO3 genes also show several neurodevelopmental defects." (PMID 32118035, 2020).
Cirrhosis (1 paper, 2022). A chronic disorder of the liver in which liver tissue becomes scarred and is partially replaced by regenerative nodules and fibrotic tissue resulting in loss of liver function. "Genome‐wide association study (GWAS) summary statistics were extracted from seven studies (>1.7 million participants) for variants near ACVR2A, ALB, CIDEB, FOXO1, GPAM, NEAT1 and TNRC6B for: aminotransferases, liver fat, HbA1c, diagnosis of NAFLD, ARLD and cirrhosis." (PMID 35474605, 2022).
depression (1 paper, 2025). "Furthermore, genes (TNRC6B, HSPA8), and pathways (FoxO- and Hippo signaling pathway) were predicted to be relevant in the pathway regarding the influence of depression on bone metabolism." (PMID 39869252, 2025).
diabetes (1 paper, 2021). "These included several genes not previously implicated in diabetes, GIGYF1, TNRC6B and PFAS, as well as GCK, HNF1A and PDX1, known MODY genes." (PMID 34732801, 2021).
esophageal squamous cell carcinoma (1 paper, 2023). Esophageal squamous cell carcinoma (ESCC) is a type of esophageal carcinoma (EC) that can affect any part of the esophagus, but is usually located in the upper or middle third. "This study identified a previously unknown tumor suppressor circular RNA called circ‐TNRC6B, which was significantly downregulated in esophageal squamous cell carcinoma (ESCC) tissues." (PMID 37014625, 2023).
juvenile polyarticular arthritis (1 paper, 2013). "Upregulation of CALR, PRDM1, STAT1, TAGAP and TNRC6B has been associated elsewhere with adult rheumatoid arthritis or juvenile polyarticular arthritis." (PMID 24000795, 2013).
leiomyoma (1 paper, 2018). A well-circumscribed benign smooth muscle neoplasm characterized by the presence of spindle cells with cigar-shaped nuclei, interlacing fascicles, and a whorled pattern. "rs739187 is about 3 Mb away from the leiomyoma variant rs12484951 (TNRC6B) and the 2 variants are not correlated either in Europeans (r2 = 0.0064) or African–Americans (r2 = 0.017)." (PMID 30194396, 2018).
lymph node metastasis (1 paper, 2023). "Multivariate analysis revealed that lymph node metastasis and distant metastasis were independent risk factors for OS, while circ‐TNRC6B expression was an independent protective factor for OS in patients with ESCC." (PMID 37014625, 2023). "Univariate analysis indicated that circ‐TNRC6B expression, lymph node metastasis, and distant metastasis were significantly correlated with OS." (PMID 37014625, 2023). "The expression level of circ‐TNRC6B was significantly and negatively correlated with T stage but was not significantly correlated with age, gender, lymph node metastasis, distant metastasis, and pathological grade." (PMID 37014625, 2023).
nasopharyngeal carcinoma (1 paper, 2022). A carcinoma arising from the nasopharyngeal epithelium. "First, we expressed HA-tagged RISC components (Ago2, TNRC6A TNRC6B) with or without BGLF2-FLAG in HONE-1 (EBV-negative nasopharyngeal carcinoma) cells and stained the cells for HA and FLAG." (PMID 35007297, 2022).
osteoporosis (1 paper, 2022). A condition of reduced bone mass, with decreased cortical thickness and a decrease in the number and size of the trabeculae of cancellous bone (but normal chemical composition), resulting in increased fracture incidence. "Target genes with the highest number of miRNAs were DGKH, TNRC6B, ZNF704, INO80D and NFAT5, but according to the literature, none of these were ever directly associated with PTH or osteoporosis." (PMID 36011354, 2022).
prostate tumour (1 paper, 2023). "According to the data from microarray analysis on 52 paired PCa samples from PCa tumour area and non-pathological tissue obtained from TCGA, we observed that relative expression of the TNRC6B gene was significantly upregulated in prostate tumour tissue." (PMID 37978493, 2023). "Our results indicate that at least 3/4 downregulated exomiRNAs from prostate tumour tissue may positively regulate the expression of the TNRC6B gene because binding sites were predicted, a fact that may involve this gene in the impairing of multiple signalling pathways linked to PCa development." (PMID 37978493, 2023). "While for prognosis by using serum PSA levels and CDK6, TNRC6B, and AGO1 expression in prostate tumour tissue, the CART chart showed that a patient with PSA values ≤ 7.65 ng/ml, will harbour a high-risk PCa if the relative expression level of TNRC6B in PCa tissue is ≤ 5.618 (27%)." (PMID 37978493, 2023). "We checked the expression levels of CDK6, TNRC6B, AGO1, AGO3, and TNRC6A in PCa tissues, based on data from 465 prostate tumour samples obtained from TCGA-PRAD database, and stratified according to the 2014 ISUP-GG into low-risk (ISUP I and II) and high-risk (ISUP III, IV, and V)." (PMID 37978493, 2023).
Tinnitus (1 paper, 2022). Tinnitus is an auditory perception that can be described as the experience of sound, in the ear or in the head, in the absence of external acoustic stimulation. "The genomic loci involving PSAP and TNRC6B showed suggestive association with tinnitus." (PMID 36581688, 2022). "We obtained SNPs in AGO2 and TNRC6B showing association with tinnitus." (PMID 36581688, 2022). "The interplay between AGO2 and TNRC6B might influence regulatory RNA mechanisms contributing to tinnitus." (PMID 36581688, 2022).